TUT7 (terminal uridylyl transferase 7)
Description:
Uridylyltransferase that mediates the terminal uridylation of mRNAs with short (less than 25 nucleotides) poly(A) tails, hence facilitating global mRNA decay. Essential for both oocyte maturation and fertility. Through 3' terminal uridylation of mRNA, sculpts, with TUT7, the maternal transcriptome by eliminating transcripts during oocyte growth (By similarity). Involved in microRNA (miRNA)-induced gene silencing through uridylation of deadenylated miRNA targets. Also functions as an integral regulator of microRNA biogenesiS using 3 different uridylation mechanisms. Acts as a suppressor of miRNA biogenesis by mediating the terminal uridylation of some miRNA precursors, including that of let-7 (pre-let-7). Uridylated pre-let-7 RNA is not processed by Dicer and undergo degradation. Pre-let-7 uridylation is strongly enhanced in the presence of LIN28A. In the absence of LIN28A, TUT7 and TUT4 monouridylate group II pre-miRNAs, which includes most of pre-let7 members, that shapes an optimal 3' end overhang for efficient processing. Add oligo-U tails to truncated pre-miRNAS with a 5' overhang which may promote rapid degradation of non-functional pre-miRNA species. Does not play a role in replication-dependent histone mRNA degradation. Due to functional redundancy between TUT4 and TUT7, the identification of the specific role of each of these proteins is difficult. TUT4 and TUT7 restrict retrotransposition of long interspersed element-1 (LINE-1) in cooperation with MOV10 counteracting the RNA chaperonne activity of L1RE1. TUT7 uridylates LINE-1 mRNAs in the cytoplasm which inhibits initiation of reverse transcription once in the nucleus, whereas uridylation by TUT4 destabilizes mRNAs in cytoplasmic ribonucleoprotein granules.
Synonyms: KIAA1711; ZCCHC6; FLJ13409; PAPD6; TENT3B
Tractability: Small molecule: a structure with a bound ligand is known. PROTAC: ubiquitination databases record sites on it.
Gene: Protein-coding gene on chromosome 9 (86,287,725 to 86,354,541, reverse strand). Ensembl gene ENSG00000083223.
Subcellular location: Cytoplasm
Subcellular location (Human Protein Atlas): Cytosol; Nucleoplasm
Pathways (Reactome):
Developmental Biology: Z-decay: degradation of maternal mRNAs by zygotically expressed factors; Zygotic genome activation (ZGA)
Metabolism of RNA: Deadenylation of mRNA
Gene Ontology:
Molecular function: miRNA binding; protein binding; RNA binding; RNA uridylyltransferase activity; uridylyltransferase activity; nucleic acid binding; nucleotidyltransferase activity; zinc ion binding
Biological process: histone mRNA catabolic process; miRNA metabolic process; pre-miRNA processing; RNA 3'-end processing; transposable element silencing by mRNA destabilization; oocyte maturation; polyuridylation-dependent mRNA catabolic process
Cellular component: cytoplasm; cytosol
Genetic constraint (gnomAD): Loss-of-function variants: 24 observed, 123.5 expected, observed/expected ratio (o/e) 0.19, 90% interval 0.14 to 0.27. The upper end of that interval is the gene's LOEUF score, 0.27, which puts it in group 1 of 6, group 1 being the genes least tolerant of losing a copy. Missense variants: 1,126 observed, 1,517.3 expected, observed/expected ratio (o/e) 0.74, 90% interval 0.71 to 0.78. Synonymous variants: 479 observed, 539.4 expected, observed/expected ratio (o/e) 0.89, 90% interval 0.82 to 0.96.
Homologues: Orthologues: chimpanzee TUT7 (99% identical), macaque TUT7 (95% identical), dog TUT7 (88% identical), rabbit TUT7 (86% identical), guinea pig TUT7 (82% identical), rat Tut7 (80% identical), mouse Tut7 (79% identical), tropical clawed frog tut7 (56% identical), Caenorhabditis elegans cid-1 (20% identical), Caenorhabditis elegans gld-2 (11% identical), Caenorhabditis elegans pup-2 (9% identical), Caenorhabditis elegans C53A5.16 (5% identical), and 3 more. Paralogues in human: TUT4 (39% identical), TUT1 (9% identical), TENT2 (8% identical), MTPAP (7% identical).
Diseases named in the same sentence as TUT7 in open-access papers:
TUT7 is named in the same sentence as 17 diseases in open-access papers, as found by Europe PMC text mining. Sharing a sentence is not in itself a finding about the gene and the disease. The quoted sentences say what the papers report.
cervical cancer (1 paper, 2025). A primary or metastatic malignant neoplasm involving the cervix. "Additionally, human papilloma virus (HPV)-induced cervical cancer is associated with the downregulation of TUT7/ZCCHC6 and the upregulation of TENT2/PAPD4/GLD2 and TENT4A/PAPD7, although the impact of these changes on miRNA 3′ tailing remains to be determined." (PMID 40243428, 2025).
male infertility (1 paper, 2024). The inability of the male to effect fertilization of an ovum after a specified period of unprotected intercourse. "Deletion of both TUT4 and TUT7 in pre-meiotic germ cells by using Stra8-Cre mice leads to spermatogenic arrest in the late pachytene stage, accompanied by cell apoptosis, ultimately resulting in spermatogenic failure and male infertility." (PMID 39310107, 2024).
ovarian carcinoma (1 paper, 2022). A malignant neoplasm originating from the surface ovarian epithelium. "Contrary to a previous study in cervical-derived HeLa cells, which concluded that the functional activity of both TUT4 and TUT7 is vital for cell viability, our data show that TUT4 and TUT7 are not required for viability in the prostate cancer cell line DU145 and the ovarian cancer cell line IGROV1." (PMID 34949722, 2022).
pterygium (1 paper, 2025). A wedge-shaped fibrovascular lesion arising from the bulbar conjunctiva and extending to the cornea. "In conclusion, the progression of pterygium is regulated by TUT7 through the uridylylation of MCPIP1 mRNA." (PMID 40238115, 2025). "In the pterygium mouse model, TUT7 expression was found to be significantly elevated, exhibiting a negative correlation with MCPIP1 expression." (PMID 40238115, 2025). "Given the high expression of TUT7 in pterygium tissue, additional evidence was sought to establish its impact on pterygium progression by regulating the MCPIP1 mRNA stability." (PMID 40238115, 2025). "Conversely, TUT7 uridylylation modulated MCPIP1’s regulation of pterygium." (PMID 40238115, 2025). "However, the regulatory mechanisms by which TUT7 influences MCPIP1 in pterygium remain to be elucidated." (PMID 40238115, 2025). "The function of MCPIP1 was weakened by TUT7, which reduced the stability of MCPIP1 mRNA and thus alleviated the negative regulatory effect of MCPIP1 on pterygium." (PMID 40238115, 2025). "In line with this, the effects of TUT7 and MCPIP1 coexpression on fibrosis and autophagy in the pterygium were investigated." (PMID 40238115, 2025). "Our research revealed a significant upregulation of TUT7 in both the pterygium mouse model and HPF cells, exhibiting a strong negative correlation with MCPIP1 expression." (PMID 40238115, 2025).
cancer (10 papers, 2015 to 2025). A tumor composed of atypical neoplastic, often pleomorphic cells that invade other tissues. "Due to its involvement in the LIN28A:let-7 axis, special attention has been brought on the efficacy of targeting TUT4 and TUT7 to negatively impact cancer proliferation and progression." (PMID 34949722, 2022). "With an aim toward the development of anti-cancer drugs, small molecule compounds that inhibit the Lin28-dependent TUT7 activity have been isolated and other small compounds that block the interaction between Lin28 and let-7 have been reported." (PMID 31036859, 2019). "The effects of TUT4 and TUT7 are proving to be context and (cancer) cell type dependent." (PMID 39054354, 2024). "TUT4 and the closely related TUT7 are non-templated poly(U) polymerases required at different stages of development, and their mis-regulation or mutation has been linked to important cancer pathologies." (PMID 34719327, 2021). "Zcchc11 (TUT4) and Zcchc6 (TUT7) modify, through 3′ uridylation, a specific microRNA group that shares a TUTase recognition sequence motif and targets proteins belonging to the Homeobox family in P19 embryonal carcinoma cells from mouse." (PMID 34178993, 2021). "In mouse embryonic stem cells (mESCs) and certain cancer cells, TUT4/ZCCHC11 or TUT7/ZCCHC6 catalyze oligo-uridylation of pre-let-7, leading to its destabilization." (PMID 40243428, 2025). "This study reveals the molecular basis for mono- versus oligo-uridylation by TUT7/4, as determined by the presence of LIN28A, and thus their mechanism of action in the regulation of cell fate and in cancer." (PMID 39054354, 2024). "In cancers such as glioblastomas overexpressing TUT4 and TUT7, pre-miR-324 is uridylated at the 3′ end, which leads to the 3′ arm-derived miR-324-3p being more abundant than the miR-342-5p derived from the 5′ arm of the same precursor hairpin." (PMID 34949722, 2022). "In embryonic stem cells and cancer cells, TUT4 and TUT7 (TUT4/7) have been shown to oligo-uridylate precursors of let-7 family miRNAs in concert with the processivity factor Lin28." (PMID 25979828, 2015).
tumor (4 papers, 2015 to 2024). "The CM from TUT7‐overexpressing cells polarized macrophages to a tumor‐supporting type, as evident by increased levels of M2 markers." (PMID 38342611, 2024). "The terminal RNA uridyl transferases TUT4 and TUT7 (TUT4/7) are the enzymes responsible for catalyzing the addition of Us at the 3′ end of miRNAs such as the tumor suppressor let-7s, to regulate their expression levels." (PMID 34949722, 2022). "Tumor-suppressor let-7 pre-microRNAs (miRNAs) are regulated by terminal uridylyltransferases TUT7 and TUT4 that either promote let-7 maturation by adding a single uridine nucleotide to the pre-miRNA 3′ end or mark them for degradation by the addition of multiple uridines." (PMID 39054354, 2024). "The human terminal uridyl transferases TUT4 and TUT7 (TUT4/7) catalyze the additions of uridines at the 3′ end of RNAs, including the precursors of the tumor suppressor miRNA let-7 upon recruitment by the oncoprotein LIN28A." (PMID 34949722, 2022).
Cardiovascular disease (1 paper, 2024). "Among these, 10 regions, proximal to or within the genes OVAAL, BMP3, RIOK1, AC096553.5, MCPH1, KCNU1, GLIS3, TUT7, TRIB3, and SYNDIG1, represent novel associations with MI and have not been previously linked to Cardiovascular disease (CVD)-related traits." (PMID 38725839, 2024).
TUT7 also shares sentences with these, for which no sentence is quoted: infection (2 papers); anemia (1); Arthritis (1); bacterial pneumonia (1); colitis (1); embryonal carcinoma (1); hemoglobinopathies (1); pneumonia (1); prostate carcinoma (1); thalassemia (1).